DSG3 (desmoglein 3)
Diseases named in the same sentence as DSG3 in open-access papers (continued):
Sharing a sentence is not in itself a finding about the gene and the disease.
Psoriasiform dermatitis (1 paper, 2018). A skin abnormality characterized by redness and irritation, with thick, red skin that displays flaky, silver-white patches (scales). "Because, animal studies have demonstrated that single helper T cell clone specific for desmoglein 3 is sufficient to recapitulate autoimmune blister formation whereas the Th17-deviated T cell clone specific for desmoglein 3 induces psoriasiform dermatitis." (PMID 30135860, 2018).
sarcoma (1 paper, 2012). A usually aggressive malignant neoplasm of the soft tissue or bone. "Histological analysis demonstrated that tumors arising in both wild-type and Dsg3−/− mice were SCCs and sarcomas, as described, and that these tumor types arose at similar proportions, irrespective of genotype." (PMID 23185521, 2012).
small cell carcinoma (1 paper, 2022). A neuroendocrine carcinoma composed of small malignant cells which are often said to resemble "oat cells" under the microscope. "Notably, the single small-cell carcinoma component showed 0% DSG3 immunoreactivity." (PMID 35251162, 2022).
small cell lung carcinoma (1 paper, 2022). Small cell lung cancer (SCLC) is a highly aggressive malignant neoplasm, accounting for 10-15% of lung cancer cases, characterized byrapid growth, and early metastasis. "In summary, the DSG3 positivity rate was 18% (4/22) for adenocarcinoma cases and 0% for both small-cell lung carcinoma and large B-cell lymphoma cases." (PMID 35251162, 2022). "All small-cell lung carcinoma and large B-cell lymphoma cases showed zero DSG3 immunoreactivity." (PMID 35251162, 2022). "Therefore, our results of 0% DSG3 immunoreactivity in lung small-cell carcinoma were helpful in this aspect." (PMID 35251162, 2022). "With a 5% immunoreactivity cutoff, DSG3 positivity was 100% in all 63 SCC components, 18% in adenocarcinoma cases, and 0% in small-cell lung carcinoma or large B-cell lymphoma cases." (PMID 35251162, 2022).
tetanus (1 paper, 2019). A serious infectious disorder that follows wound contamination by the Gram-positive bacterium Clostridium tetani. "Our study, among others, has shown that while anti-Dsg3 titers drop with Rtx treatment, tetanus titers are unaffected." (PMID 31340153, 2019).
visceral leishmaniasis (1 paper, 2020). A severe form of leishmaniasis characterized by irregular bouts of fever, substantial weight loss, swelling of the spleen and liver, and anemia (which may be serious). "Further, it has been demonstrated that anti-Dsg1 and -Dsg3 antibodies were more prevalent in subjects with visceral leishmaniasis." (PMID 33108348, 2020).
vulvar carcinoma (1 paper, 2022). "Our previous study based on vulvar carcinoma A431 cell line has implicated that DSG3 promotes cancer cell migration and invasion." (PMID 35000271, 2022).
cancer (32 papers, 2010 to 2024). A tumor composed of atypical neoplastic, often pleomorphic cells that invade other tissues. "DSG3 median gene expression levels were the highest in HNSC among all TCGA cancer types (median = 155 FPKM), and its encoded protein was detected in two of four HNSC patients via membranous and/or cytoplasmic antibody staining in the HPA Pathology Atlas." (PMID 37835579, 2023). "Loss of adhesion molecules such as DSG3 as well as E-cadherin occurs when cancer cells undergo dedifferentiation or EMT." (PMID 38067138, 2023). "Overall, the GO term enrichment analysis collectively provides valuable insights into the roles and functions of DSG3 and its associated gene products in a cancer cell background." (PMID 38067138, 2023). "Paradoxically, evidence has emerged that shows an upregulation of some desmosomal components, such as Dsg2, Dsg3 and Pkp3 in cancer, in association with cancer progression and/or reduced survival." (PMID 25629808, 2015). "The relative expression of plakoglobin in nuclear fraction was decreased considerably in the cancer cell lines, but minimal alteration in the total protein extracts, suggestion that DSG3 over-expression was associated with plakoglobin translocation." (PMID 23737966, 2013). "To investigate whether Dsg3 deficiency can, similarly to Perp loss, sometimes promote cancer, we sought to examine tumor development in Dsg3−/− mice." (PMID 23185521, 2012). "Accumulating evidence implicates DSG3 in the progression of various cancer types, notably squamous cell carcinoma." (PMID 38900156, 2024). "Reported evidence has indicated the facilitation of cancer cell migration and invasion through the regulation of Ezrin activation by DSG3 (23752190)." (PMID 38900156, 2024). "In general, this finding aligns with the idea that connexins act as cancer suppressors, and the increased level of DSG3 further contributes to the reduction in Cx43 expression." (PMID 38067138, 2023). "We observed significant differential expression of DSG3 in pan-cancer, particularly in PC tissues, and higher expression levels of DSG3 were correlated with higher histological grade, pathological stage, and T-stage." (PMID 37845218, 2023). "Genes with known implications in cancer, such as MMP-13, KRT84, OLFM4, GJA1, AMOT and ADAMTS1, were strongly linked to DSG3 overexpression." (PMID 38067138, 2023). "Lastly, DSG3 can function as an oncogene and facilitate cancer growth and invasion through protein kinase C or DSG3-plakoglobin-TCF/LEF pathways." (PMID 35251162, 2022). "Concordantly, upregulation of DSG3 is found in cancers of various organs, including the head and neck." (PMID 35000271, 2022). "P25 TRAMP CRIPSCs also had upregulated genes related to cancer development and drug resistance, such as Aldh3a1, Ly6d, Il33, Dsg3, and Col17a1." (PMID 35841025, 2022). "In support, ectopic expression of DSG3 in the A431 carcinoma cell line elicits activation of several signalling pathways that lead to enhanced cell migration and invasion." (PMID 35000271, 2022). "Nevertheless, paradoxically, a potential role of DSG3 as an oncogene in cancer development has been emerging." (PMID 34206820, 2021). "Several earlier studies indicated a favorable effect of DSG3 reduction in carcinogenesis with its decrease correlated with a more aggressive cancer phenotype." (PMID 34206820, 2021). "This review will focus on recent advances with regard to the role of Dsg3 in cancer progression and metastasis." (PMID 25629808, 2015). "Using two models of skin carcinogenesis a recent study investigated the role of Dsg3 in cancer suppression." (PMID 25629808, 2015). "Taken together, these studies are consistent with the notion that Dsg3 plays a positive role in cancer progression and metastasis." (PMID 25629808, 2015). "Evidence of the Dsg3 down-regulation in the context of cancer development and progression is comparatively less." (PMID 25629808, 2015).
cancer (continued). "Recent studies have shed light that Dsg3 also acts as a key regulator in various intracellular signal pathways that are likely hijacked in cancer and promote cancer cell invasion and dissemination." (PMID 25629808, 2015). "Further study of Dsg3 in cancer cells and their microenvironment is required to advance our knowledge." (PMID 25629808, 2015). "This review will discuss recent advances which support the role of desmoglein 3 in cancer progression." (PMID 25629808, 2015). "In line with this notion, an in vitro study based on cancer cell lines shows that Dsg3 overexpression increases the tyrosine phosphorylation and activity of β-catenin as well as a reduction of E-cadherin." (PMID 25629808, 2015). "In line with this, in vitro studies based on overexpression of human Dsg3 in cancer cell lines have shed light on its signalling role that regulates a variety of cellular processes including cell cohesion and migratory behaviour." (PMID 25629808, 2015). "The overexpression of Dsg3 in carcinoma cells has been shown to increase Rac1 and Cdc42 activities and to a lesser extent RhoA, accompanied by pronounced lamellipodia and filopodia and an enhanced rate of actin turnover." (PMID 25629808, 2015). "Consistently, DSG3 over-expression and plakoglobin translocation was found in the cancer tissues, in concurrence with up-regulations of c-myc, cyclin D1 and MMP-7." (PMID 23737966, 2013). "In conclusion, we found that DSG3 functions as an oncogene and facilitates cancer growth and invasion in HNC cells through the DSG3-plakoglobin-TCF/LEF pathway." (PMID 23737966, 2013). "Our results showed that DSG3 promotes cancer cell growth and invasion through a plakoglobin-mediated signaling pathway." (PMID 23737966, 2013). "The DSG3 knockdown stable cancer cell lines (SAS-sh2) and the empty vector transfection cell line as a control were subcutaneously injected into the mice." (PMID 23737966, 2013). "In the cell line analyzed, DSG3 showed high expression in two cancer cell lines, in contrast to undetectable level in two normal keratinocytes." (PMID 23737966, 2013). "Continued unraveling of the roles of Dsg3 and other desmosomal constituents in carcinogenesis in different contexts will be important for ultimately improving cancer diagnosis, prognostication, and treatment." (PMID 23185521, 2012). "However, the role of DSG3 in cancer remains not fully understood, and contradictory findings have been reported in the literature." (PMID 38067138, 2023). "This theory can also explain what we have reported previously that DSG3 overexpression in A431 carcinoma cells promotes cell migration and invasion since in this model system, DSG3 activates Src signalling, among others, and downregulate E‐cadherin‐mediated adherens junctions." (PMID 35000271, 2022). "DSG3 was reported to promote the growth and invasion of cancer cells." (PMID 34980950, 2021). "Overexpression of DSG3 may be conducive to its oncogenic signaling activity, leading to accelerated movement and proliferation of cancer cells." (PMID 34203070, 2021). "Is the overexpression of DSG3 in cancer involved in post-translational regulation, such as DSG2?" (PMID 34203070, 2021). "Similarly, in addition to enhancing cell adhesion, DSG3 also promotes cancer progression through intercellular signaling molecular transduction." (PMID 34203070, 2021). "We evaluated DSG3 as a novel target by selecting an epitope that exerts efficacy against cancer with no pathogenic effects in normal tissues." (PMID 30239818, 2018). "Similarly, the DSG3-plakoglobin-TCF/LEF-Myc/cyclin D1/MMP signaling pathway facilitates cancer growth and invasion." (PMID 26933815, 2016). "Furthermore, in vitro studies have demonstrated that overexpression of desmoglein 3 in cancer cell lines activates several signal pathways that have an impact on cell morphology, adhesion and locomotion." (PMID 25629808, 2015).
cancer (continued). "Increased expression of Dsg3 in cancer cell lines has been demonstrated to elicit a significant increase in the tyrosine phosphorylation of Src and its downstream targets of adherens junction proteins, E-cadherin, β-catenin and p120 with a consequence of decreased E-cadherin expression." (PMID 25629808, 2015). "Nevertheless, it was demonstrated by a group of researchers that the RNAi mediated Dsg3 silencing in head and neck SqCC lines reduces tumour growth and metastasis in xenograft studies in BALB/C nude mice indicating the therapeutic potential of targeting Dsg3 in preventing cancer progression." (PMID 25629808, 2015). "Furthermore, in vivo investigation in transgenic model with Dsg3 overexpression will particularly benefit by providing new insights into how exactly this gene is involved in cancer development and progression." (PMID 25629808, 2015). "In this report, the overexpression of Dsg3 enhanced phosphorylation and localisation of Ezrin at basal plasma membrane domains, events indicative of the aberrant regulation of Ezrin in cancer progression." (PMID 25629808, 2015). "Taken together, these findings support the signalling role of Dsg3 which could potentially contribute to cancer development or suppression." (PMID 25629808, 2015). "To choose a set of candidate markers optimally covering the spectrum of NSCLC cancers, we selected two markers from each of these covariation groups for further validation in addition to DSG3, which seemed to have an independent primary tumor expression pattern." (PMID 23671585, 2013). "Over-expression of DSG3 in cancers may be just an initial step that affects the regulation of cell fate." (PMID 23737966, 2013). "Moreover, overexpression of DSG3 is correlated with malignant progression of human sinonasal inverted papillomas and with development of cancers of the head, neck and lung, also reflecting an oncogenic function for DSG3." (PMID 23185521, 2012). "Our analysis of the contribution of Dsg3 to cancer development in these two settings suggest that, unlike E-cadherin, Dsg3 loss is not sufficient to promote carcinogenesis and that Dsg3 does not display clear tumor suppressor activity." (PMID 23185521, 2012). "Therefore, adhesion molecules like DSG3 may be vital in cancer cell adhesion, signalling and survival." (PMID 38067138, 2023). "Furthermore, a correlation between the expression levels of Dsg3 and tumour progression and metastasis has been reported, suggesting that in a given context Dsg3 may contribute to cancer progression." (PMID 25629808, 2015). "However, recently several studies have shown that various desmosomal components, including desmoglein 3, are up-regulated in cancer with increased levels of expression correlating with the clinical stage of malignancy, implicating their potentiality to serve as a diagnostic and prognostic marker." (PMID 25629808, 2015). "However, the fact that a clear cancer predisposition has not been noted in these patients suggests further that loss of Dsg3 is not sufficient for cancer development in stratified epithelia." (PMID 23185521, 2012). "To better understand the role of desmosomal cadherins in cancer, we employed mice lacking the desmosomal cadherin Dsg3, which are viable yet in which Dsg3 plays key physiological roles in cell-cell adhesion, as Dsg3 deficiency induces blisters of the oral mucosa and hair follicle defects." (PMID 23185521, 2012). "Moreover, RNAi knockdown of Dsg3 in cancer cell lines resulted in inhibition of cell growth, cell migration and invasion, suggesting that the role of Dsg3 may be more complex than simply just facilitating normal cell-cell adhesion." (PMID 21151980, 2010). "Using these eight cancer types, we defined a set of 76 core basal genes, which include the classic markers KRT5, KRT6A/B/C, and DSG3." (PMID 38791964, 2024).
cancer (continued). "Among these genes, DSG1 and DSG3 are components of intercellular desmosome junctions, which mediate cell‐cell adhesion and correlate with EMT in cancer." (PMID 38090381, 2023). "DSG1 and DSG3 are components of intercellular desmosome junctions, which mediate cell‐cell adhesion and correlate with EMT in cancer progression." (PMID 38090381, 2023). "In line with this notion, immunohistochemistry of DSG3 in cutaneous SCC showed enhanced positivity, with the signals positively correlated with poor differentiation status of cancer (our unpublished data)." (PMID 34206820, 2021). "Therefore, a possible explanation for the difference in cancer predisposition of mice deficient for Perp and for Dsg3 following chronic UVB treatment is that the potential consequences of Dsg3 deficiency may be compensated by induction of the other desmogleins." (PMID 23185521, 2012). "In particular, we focused on Dsg3 and its role in SCC development, using two different models, and we found that the role of Dsg3 in cancer varies slightly according to context." (PMID 23185521, 2012). "Although not yet investigated, neoantigens that mimic self-antigens derived from desmosomal and hemidesmosomal proteins could be relevant, considering that proteins such as Dsg3, BP180, BP230, and integrin α6β4 are overexpressed in epithelial carcinomas." (PMID 39584995, 2024). "The pathway analysis (SRPlot) identified several important, previously unknown pathways concerning DSG3, including the focal adhesion pathway, protein digestion and absorption pathway, ECM-receptor interaction pathway and proteoglycan in cancer, etc.." (PMID 38067138, 2023). "This is partly due to the lack of transgenic animal models with overexpression of DSG3 that will enable the study of its role in carcinogenesis and cancer spreading." (PMID 34206820, 2021). "Mechanisms demonstrated that DSG3 regulates c-Jun/activator protein 1 (AP-1) activity and protein kinase C (PKC)-mediated phosphorylation of Ezrin-Thr567, which contributes to the motility of cancer cells." (PMID 34203070, 2021). "Desmoglein-3 (Dsg3), the Pemphigus Vulgaris (PV) antigen (PVA), plays an essential role in keratinocyte cell–cell adhesion and regulates various signaling pathways involved in the progression and metastasis of cancer where it is upregulated." (PMID 31582719, 2019). "Although Dsg3 is shown to play a positive role in oncogenesis evidence suggests that Dsg3 may not function as a main driver in cancer formation but rather as a factor that promotes cancer progression." (PMID 25629808, 2015). "While a gradual loss of DSG3 and E‐cadherin was detected in FOM cell lines during cancer transformation, this pattern was not seen in BM cell lines in which moderate E‐cadherin levels retained in three cancer lines in contrast to D17‐TERT that had little or no detection." (PMID 35000271, 2022). "KRT19, CEACAM5, EPCAM, DSG3, SFTPA, SFTPC and SFTPB mRNA levels were initially validated by real-time reverse transcription PCR-based quantification in 16 NSCLC tumors and 22 LNs and 12 PB samples from individuals without known cancer." (PMID 23671585, 2013).